MIR92B (microRNA 92b)
Synonyms: hsa-mir-92b; MIRN92B; mir-92b
Gene: MicroRNA gene on chromosome 1 (155,195,177 to 155,195,272, forward strand). Ensembl gene ENSG00000284586.
Diseases named in the same sentence as MIR92B in open-access papers:
MIR92B is named in the same sentence as 2 diseases in open-access papers, as found by Europe PMC text mining. Sharing a sentence is not in itself a finding about the gene and the disease. The quoted sentences say what the papers report.
lung adenocarcinoma (1 paper, 2025). A carcinoma that arises from the lung and is characterized by the presence of malignant glandular epithelial cells. "Many of the identified CNAs also included well-known cancer-related miRNA genes, including MIR92B (ch1q21), MIR30B (ch8q24), and MIR30D (ch8q24), whose frequent amplifications in lung adenocarcinoma have been reported previously, and many others that have not been reported previously." (PMID 40867048, 2025).
MIR92B also shares sentences with these, for which no sentence is quoted: cancer (1 paper).